REEP3 (receptor accessory protein 3)
Description:
Microtubule-binding protein required to ensure proper cell division and nuclear envelope reassembly by sequestering the endoplasmic reticulum away from chromosomes during mitosis. Probably acts by clearing the endoplasmic reticulum membrane from metaphase chromosomes.
Synonyms: C10orf74; Yip2b
Tractability: Antibody: UniProt predicts a signal peptide or a membrane-spanning region. PROTAC: ubiquitination databases record sites on it; its protein half-life has been measured.
Gene: Protein-coding gene on chromosome 10 (63,521,397 to 63,625,128, forward strand). Ensembl gene ENSG00000165476.
Subcellular location: Endoplasmic reticulum membrane
Gene Ontology:
Molecular function: protein binding; microtubule binding
Biological process: mitotic nuclear membrane reassembly; nuclear envelope organization; endoplasmic reticulum tubular network organization
Cellular component: cytoplasmic microtubule; endoplasmic reticulum membrane; endoplasmic reticulum tubular network
Genetic constraint (gnomAD): Loss-of-function variants: 8 observed, 12.19 expected, observed/expected ratio (o/e) 0.66, 90% interval 0.38 to 1.18. The upper end of that interval is the gene's LOEUF score, 1.18, which puts it in group 5 of 6, group 1 being the genes least tolerant of losing a copy. Missense variants: 108 observed, 119.65 expected, observed/expected ratio (o/e) 0.9, 90% interval 0.77 to 1.06. Synonymous variants: 41 observed, 38.58 expected, observed/expected ratio (o/e) 1.06, 90% interval 0.83 to 1.38.
Homologues: Orthologues: chimpanzee REEP3 (99% identical), pig REEP3 (96% identical), dog REEP3 (93% identical), mouse Reep3 (92% identical), rabbit REEP3 (92% identical), guinea pig REEP3 (89% identical), rat Reep3 (89% identical), tropical clawed frog reep3 (73% identical), zebrafish reep3b (67% identical), zebrafish reep3a (62% identical), macaque REEP3 (55% identical), Caenorhabditis elegans T19C3.4 (32% identical), and 6 more. Paralogues in human: REEP4 (53% identical), REEP1 (51% identical), REEP2 (49% identical), REEP5 (18% identical), REEP6 (17% identical).
Diseases named in the same sentence as REEP3 in open-access papers:
REEP3 is named in the same sentence as 21 diseases in open-access papers, as found by Europe PMC text mining. Sharing a sentence is not in itself a finding about the gene and the disease. The quoted sentences say what the papers report.
depression (3 papers, 2021 to 2023). "REEP3 is associated with depression, Alzheimer’s disease, obsessive-compulsive disorder, and autism." (PMID 37818043, 2023). "We detected high impact variants in genes previously implicated in depression (e.g. Gnat2), depression-like behavior (e.g. Prlr, Nlrp1a), other psychiatric disease (e.g. Pou6f2, Kdm5a, Reep3, Wdfy3), and responses to psychological stressors (e.g. Pigr)." (PMID 34285244, 2021).
autism (2 papers, 2023). Persistent deficits in social interaction and communication and interaction as well as a markedly restricted repertoire of activity and interest as well as repetitive patterns of behavior. "The disruption of REEP3 expression due to a position effect could lead to autism." (PMID 37818043, 2023).
hepatocellular carcinoma (2 papers, 2020 to 2023). A malignant tumor that arises from hepatocytes. "Surprisingly, circFAT1 stimulates the progression of hepatocellular carcinoma by sponging miR-30a-5p for regulating REEP3 expression." (PMID 37238941, 2023).
neuroblastoma (1 paper, 2017). Neuroblastoma (NB) is the most common solid, extracranial childhood tumor. "CTTNBP2 (synapse maintenance) and REEP3 (vesicle trafficking) are enriched for regulatory variants, of which at least six (35%) alter transcription factor-DNA binding in neuroblastoma cells." (PMID 29042551, 2017).
Obesity (1 paper, 2021). Accumulation of substantial excess body fat. "Further, we have identified a novel ER-associated regulator REEP3, which promotes adipogenesis in a m6A-independent manner and provides a potential therapeutic target for obesity research." (PMID 34790688, 2021).
oral diseases (1 paper, 2021). "Some studies have found circFAT1 can act as a sponge for miR-30a-5p in competitive combination with REEP3, thus influencing the progression of HCC, but there is no relevant research on the biological characteristics of circFAT1 and its role in oral diseases." (PMID 35003269, 2021).
osteosarcoma (1 paper, 2023). A usually aggressive malignant bone-forming mesenchymal neoplasm, predominantly affecting adolescents and young adults. "Furthermore, a disease‐free survival (DFS) predictor model of osteosarcoma, including ZNF720, REEP3, CNNM2, and CGREF1, can be created using TARGET datasets, demonstrating that a combination of multiple genes may be responsible for cisplatin resistance." (PMID 36408691, 2023).
pancreatic cancer (1 paper, 2024). "Given the differential expression of REEP3 in pancreatic cancer tissues compared to normal tissues, this gene has the potential to serve as a diagnostic and prognostic marker in pancreatic cancer." (PMID 38879709, 2024). "Through the analysis of multiple datasets including TCGA, GTEX, GEO and Kaplan–Meier Plotter databases, we observed a significant increase in REEP3 mRNA expression in pancreatic cancer patients, which was associated with unfavorable prognosis." (PMID 38879709, 2024). "REEP3 is a potential diagnostic, prognostic marker and immunotherapeutic target for pancreatic cancer." (PMID 38879709, 2024). "Lastly, exploring the interactions between REEP3 and other molecules through studying other related genes and signaling pathways, to obtain a deeper understanding of the mechanisms underlying the development of pancreatic cancer." (PMID 38879709, 2024). "Additionally, the expression of REEP3 was found to be associated with the prognosis of pancreatic cancer at different stages." (PMID 38879709, 2024). "Since the expression of REEP3 in pancreatic cancer tissue significantly deviates from that in normal tissue, there arises a speculation regarding REEP3’s potential diagnostic and prognostic significance in pancreatic cancer." (PMID 38879709, 2024). "The study initially examined the differential expression of the REEP3 gene in normal tissues and pancreatic cancer tissues using data from TCGA, GTEx and GEO databases." (PMID 38879709, 2024). "Secondly, further exploration of the role of REEP3 in pancreatic cancer metastasis and prognosis, as well as its potential value in personalized treatment." (PMID 38879709, 2024). "Our study revealed significant upregulation of REEP3 expression in a broad range of cancers, including pancreatic cancer." (PMID 38879709, 2024). "In summary, the mRNA expression level of REEP3 in pancreatic cancer tissue was markedly elevated in comparison to that in normal pancreatic tissue." (PMID 38879709, 2024). "Our analysis revealed a significant up-regulation of REEP3 in several tumors, including pancreatic cancer." (PMID 38879709, 2024). "In this study, we initially analyzed the differential expression of REEP3 between pancreatic cancer tissues and normal pancreas tissues using the Cancer Genome Atlas (TCGA), GTEx and Gene Expression Omnibus (GEO) databases." (PMID 38879709, 2024). "To delve deeper into the impact of REEP3 expression on the immune characteristics of pancreatic cancer, we utilized the “ssGSEA” algorithm to compare immune cell infiltration levels between the high-expression and low-expression groups of REEP3." (PMID 38879709, 2024). "Subsequently, we conducted univariate and multivariate Cox regression analyses to assess the prognostic impact of REEP3 expression on pancreatic cancer patients." (PMID 38879709, 2024). "Our findings demonstrated a substantial up-regulation of REEP3 mRNA expression in pancreatic cancer compared to normal tissues." (PMID 38879709, 2024). "To elucidate the potential mechanisms of REEP3 in pancreatic cancer, we identified differential expression genes and conducted functional enrichment analysis." (PMID 38879709, 2024). "Nonetheless, the biological role and mechanisms of REEP3 in pancreatic cancer patients, along with its interplay with immune infiltration, remain inadequately elucidated." (PMID 38879709, 2024). "Subsequently, we delved into the correlation between REEP3 expression and pancreatic cancer prognosis utilizing the Kaplan–Meier Plotter database." (PMID 38879709, 2024). "We conducted an analysis to investigate the relationship between REEP3 expression and immune cell infiltration in pancreatic cancer using the TIMER database." (PMID 38879709, 2024). "In summary, our study reveals the important role of REEP3 in pancreatic cancer and provides insights into its potential mechanisms." (PMID 38879709, 2024).
pancreatic cancer (continued). "These analyses revealed associations between REEP3 and other genes and provided insight into potential regulatory mechanisms of REEP3 in pancreatic cancer." (PMID 38879709, 2024). "Given the significance of immunotherapy in pancreatic cancer, we further investigated the correlation between REEP3 expression and immune checkpoint markers in pancreatic cancer patients." (PMID 38879709, 2024). "To elucidate the potential mechanism of REEP3 in pancreatic cancer, we stratified pancreatic cancer patients into two cohorts based on the median expression level of REEP3." (PMID 38879709, 2024). "Elevated REEP3 expression correlated with unfavorable outcomes in terms of both overall survival and relapse-free survival, establishing it as a notable adverse prognostic marker in pancreatic cancer." (PMID 38879709, 2024). "Furthermore, disparate expression patterns of GATA2 and REEP3 were observed in two GEO datasets, suggesting a potential interaction between GATA2 and REEP3 in the progression of pancreatic cancer." (PMID 38879709, 2024). "Its association with adverse prognosis suggests that inhibiting or interfering with REEP3 function may help suppress the growth and metastasis of pancreatic cancer." (PMID 38879709, 2024). "Future directions of research could contain the following aspects: Firstly, further investigation of the detailed mechanisms of REEP3 in pancreatic cancer development, particularly in pathways related to cell cycle regulation, cell proliferation and apoptosis." (PMID 38879709, 2024). "Notably, this expression pattern of GATA2 contrasts sharply with that of REEP3 in pancreatic cancer." (PMID 38879709, 2024). "In conclusion, these findings suggest that REEP3 expression could potentially serve as a biomarker for both the diagnosis and prognosis of pancreatic cancer patients." (PMID 38879709, 2024). "Finally, we analyzed the correlation between REEP3 expression and immune cell infiltration in pancreatic cancer." (PMID 38879709, 2024). "This suggests that REEP3 may play an important role in the development of pancreatic cancer." (PMID 38879709, 2024). "Based on our findings, REEP3 may serve as a potential therapeutic target in pancreatic cancer." (PMID 38879709, 2024). "However, the specific involvement of REEP3 in pancreatic cancer remains unclear and requires further investigation." (PMID 38879709, 2024). "The expression of REEP3 in pancreatic cancer showed a significantly higher level compared to that in normal tissues." (PMID 38879709, 2024).
schizophrenia (1 paper, 2017). A major psychotic disorder characterized by abnormalities in the perception or expression of reality. "In addition, both REEP3 and CACNA1C, which score high in this study, also significantly associate with schizophrenia and act in calcium signaling, a downstream pathway of HTR2A55–57." (PMID 29042551, 2017).
tumor (4 papers, 2020 to 2024). "Associations with clinical features were explored, along with investigating the potential role of REEP3 in tumor growth and progression." (PMID 38879709, 2024). "Recent studies have shown that REEP3 is significantly expressed in different types of tumors, with implications for tumor invasiveness and prognosis." (PMID 38879709, 2024). "Initially, we examined the expression of REEP3 across various normal and tumor tissues using the Kaplan–Meier Plotter database." (PMID 38879709, 2024). "This suggests that REEP3 could potentially enhance the migratory and invasive abilities of tumor cells by influencing cell adhesion and cytoskeletal rearrangement." (PMID 38879709, 2024). "In addition, we determined the REEP3, circFAT1 and miR‐30a‐5p expression in these tumours." (PMID 33179443, 2020). "REEP3, REEP4, TEP1 and EEPD1 was differentially expressed in 14, 17, 14, 13 tumor types, respectively." (PMID 37818043, 2023). "The GEPIA and TCGA datasets were used to analyze the expression patterns of REEP3, REEP4, TEP1, and EEPD1 in tumor tissue and normal tissue." (PMID 37818043, 2023). "As shown in, the REEP3, REEP4, TEP1, and EEPD1 had significantly higher expression in GBM tumor tissues compared to normal tissues." (PMID 37818043, 2023). "The result showed that the expression of REEP3, REEP4, TEP1, and EEPD1 was significantly higher in GBM tumor tissue." (PMID 37818043, 2023). "Taking advantage of Gene Expression Profiling Interactive Analysis (GEPIA) and The Cancer Genome Atlas Program (TCGA), we compared mRNA expression of REEP3, REEP4, TEP1, and EEPD1 between GBM tumor and normal brain tissue." (PMID 37818043, 2023). "To evaluate REEP3, REEP4, TEP1 and EEPD1 mRNA levels in multiple tumor and normal samples, we downloaded and compiled data from 11124 samples (Tumor =7260, Normal =3864) from the TCGA database." (PMID 37818043, 2023).
cancer (3 papers, 2011 to 2024). A tumor composed of atypical neoplastic, often pleomorphic cells that invade other tissues. "This confirmed that REEP3, REEP4, TEP1, and EEPD1 and their network proteins were involved in immunoregulatory functions and cancer development." (PMID 37818043, 2023). "Taken together, REEP3, REEP4, TEP1, and EEPD1 were related to many cellular functions including cell proliferation, differentiation, the pathogenesis of neurological disorders and cancer biology." (PMID 37818043, 2023).
psychiatric disease (1 paper, 2021). "Further, Pou6f2, Kdm5a, Reep3, Wdfy3 have been implicated in psychiatric diseases such as autism and Pigr was found to be involved in response to psychological stress." (PMID 34285244, 2021).
REEP3 also shares sentences with these, for which no sentence is quoted: Alzheimer disease (1 paper); endometriosis (1); gastric cancer (1); hereditary spastic paraplegia (1); Hyperinsulinemia (1); liver cancer (1); myelodysplastic syndrome (1); neurological disorders (1); obsessive-compulsive disorder (1).